PANX1 (pannexin 1)
Diseases named in the same sentence as PANX1 in open-access papers (continued):
Sharing a sentence is not in itself a finding about the gene and the disease.
Stroke (23 papers, 2012 to 2025). Sudden impairment of blood flow to a part of the brain due to occlusion or rupture of an artery to the brain. "The findings presented here highlight Panx1 as a potential important player associated with sex differences in stroke." (PMID 28445139, 2017). "Panx1 is associated with apoptosis as well as inflammation in injured neurons, and each of these responses are known to be sexually dimorphic in stroke." (PMID 28445139, 2017). "Further, opening of neuronal pannexin 1 hemichannels following anoxia caused sustained depolarization and cell death in cultured hippocampal slices, while blocking pannexin 1 hemichannels was neuroprotective in adult rodent stroke models." (PMID 32899855, 2020). "We tested the hypothesis that Panx1 plays an underlying role in mediating sex differences in stroke outcome responses." (PMID 28445139, 2017). "Recent studies suggest that using PANX1 channel blockers promotes the survival of stroke neurons and oligodendrocytes and the protection of cerebral white matter, mainly attributed to the inflammatory response mitigation by inhibiting the PANX1 channel." (PMID 37196132, 2024). "Already in 2006, ischemia-like conditions such as oxygen/glucose deprivation have been shown to open a large conductance (530 pS) channel in neurons (later identified as Panx1), which is involved in excitotoxicity and neuronal death during stroke." (PMID 36438559, 2022). "For example, PANX1 is reported to exacerbate the spread of ischemic injury in mice following stroke via the disruption of electrochemical gradients in neurons and glial cell types." (PMID 33937260, 2021). "The EC- specific Panx1 knockout mice also had resistance to middle cerebral artery occlusion (stroke model)." (PMID 29874791, 2018). "In this context, we predict the neuroprotective effects of the gonadal steroids in stroke to be co-opted by age-dependent changes in Panx1 expression and function." (PMID 28445139, 2017). "Sex differences in stroke-induced signaling cascades provide an important context for understanding why males and females possess different endogenous requirements for Panx1 to alter stroke severity." (PMID 28445139, 2017). "This striking difference between males and females underscores Panx1 as an important focal point to explain sexual dimorphisms in stroke outcome." (PMID 28445139, 2017). "Recent work investigating the role of Panxs in stroke recovery has demonstrated that knockout of both Panx1 and Panx2 improves histological and behavioral outcomes." (PMID 24409119, 2014). "Further study revealed that the PANX1 channel mediates the inflammatory response after stroke." (PMID 37196132, 2024). "The evidence has shown that the pannexin-1 channel was an important mediator of neuroinflammation, and the inhibition of pannexin-1 could reduce NLRP3 inflammasome activation after stroke." (PMID 35401398, 2022). "However, further studies are required to provide evidence for platelet PANX1 channels as a novel therapeutic target for the treatment of thrombosis in myocardial infarction or stroke." (PMID 35563450, 2022). "Several studies indicate that blockade or global deletion of Panx1 after stroke is neuroprotective." (PMID 29439712, 2018). "The specific mechanism(s) through which Panx1 affects stroke in females is unclear." (PMID 28445139, 2017). "Whether either of these two pathways affects Panx1 activity in females, subjected to stroke, is an important question to be addressed in future studies." (PMID 28445139, 2017). "Finally, little is understood regarding alterations to the Panx1 interactome under pathophysiological conditions, such as stroke." (PMID 24409119, 2014). "Panx1 forms large pore channels permeable to ions and small molecules, and is a clinically relevant protein in inflammatory conditions, stroke, and cancer." (PMID 24409119, 2014).
Stroke (continued). "Some of the changes in neurogenesis seen with brain injury, stroke and AD could conceivably involve pathological activation of Panx1 channels in NSC/NPCs." (PMID 22458943, 2012). "Inhibition of Panx1 channels with TAT-Panx308 was shown to confer neuroprotection after middle cerebral artery occlusion (MCAO) in rats and decreased infarct size after stroke." (PMID 36438559, 2022). "Preventing PANX1 phosphorylation with TAT-Panx308, an interfering peptide that mimics the COOH-terminal epitope of PANX1, reduces the size of brain lesions and rescues sensorimotor deficits after a stroke in mice." (PMID 38672234, 2024). "SMC-specific Panx1 knockout animals did not have an attenuation of myogenic tone in the cerebral or mesenteric circulation, and were not resistant to induction of stroke." (PMID 29874791, 2018). "We have only just begun to understand sex and Panx1 interactions in stroke, as no study reported to date has incorporated females into studies of Panx1 ablation and permanent MCA occlusion." (PMID 28445139, 2017). "Our work and the work of others, indicate that the opening of Pannexin-1 hemichannels and activation of purinergic receptors by extracellular ATP is essential for HIV infection, cellular migration, inflammation, atherosclerosis, stroke, and apoptosis." (PMID 24672487, 2014). "As discussed in section Brain, Panx1 and Panx2 are both expressed to varying degrees in neurons and supporting glia, and knocking out either gene individually in mice has no significant neuroprotective effects following stroke." (PMID 24600404, 2014).
glioma (17 papers, 2013 to 2023). A benign or malignant brain and spinal cord tumor that arises from glial cells (astrocytes, oligodendrocytes, ependymal cells). "Analysis of public gene expression databases reveals a positive correlation between Panx2 and post-diagnostic survival time in glioma patients; these analyses also suggest a link (albeit a much weaker one) between Panx1 and cancer in general." (PMID 24600404, 2014). "Consistent with an anti-tumor effect, exogenous Panx1 expression was associated with decreased proliferation, motility and anchorage-independent growth in cultured C6 glioma cells." (PMID 25018732, 2014). "Inhibition of P2X7 and pannexin 1 also reduces the inflammatory response of gliomas by inhibiting the expression of the NLRP2 inflammasome." (PMID 37723542, 2023). "In C6 glioma cells, the expression of PANX1 controls the actomyosin system and accelerates the assembly of multicellular C6 glioma aggregates." (PMID 35163442, 2022). "Moreover, our findings further expand the current functional implications of quercetin by suggesting that it may constitute a potential new therapeutic agent for diseases such as RMS, glioma, and hearing loss where upregulation of PANX1 has been shown to be potentially beneficial." (PMID 35194046, 2022). "Under pathological conditions, Panx1 levels were down-regulated in C6 glioma cells as compared to normal astrocytes." (PMID 35194046, 2022). "Panx1 channels have been reported to regulate the proliferation of human subcutaneous fibroblasts, glioma cell lines, neural stem cells, and progenitor cells." (PMID 33499026, 2021). "Initial reports showed that Panx1 levels are low in glioma cell lines and that Panx1 over-expression suppresses rat C6 glioma tumor formation." (PMID 30459312, 2018). "Such an analogy started during the last decade with the analysis of the brain cancer gene expression database REMBRANDT which revealed that the expression level of PANX2 and also PANX1 is positively correlated to post diagnosis survival of glioma patients." (PMID 29865195, 2018). "Other examples include the human glioma cell line U87-MG that had a significant reduction in proliferation upon Panx1 siRNA treatment." (PMID 27229305, 2016). "Earlier, Lai and colleagues demonstrated that ectopic expression of Panx1 in C6 glioma cells resulted in a dramatically altered cell morphology." (PMID 24523699, 2014). "An earlier study on C6 glioma cells engineered to express Panx1, demonstrated that ectopic Panx1 overtakes control of the actomyosin system to accelerate the compaction of multicellular C6 glioma aggregates." (PMID 24523699, 2014). "Along these lines, over-expression of Panx1 or Panx2 in rat C6 glioma cells has been shown to reduce their tumorigenicity, both in vitro and in vivo." (PMID 24600404, 2014). "A recent study in glioma cells further supported a role for Panx1 in the dynamic regulation of actin cytoskeleton remodeling." (PMID 23964896, 2013). "A study demonstrated high PANX1 mRNA expression in human glioma cell lines." (PMID 30654593, 2019). "Furthermore, a significant reduction in proliferation of U87-MG human glioma cells was noted when a PANX1 siRNA was introduced." (PMID 30654593, 2019). "Panx1 has also been shown to reduce the size of rat glioma aggregates." (PMID 30459312, 2018). "Additionally, when Panx1-GFP was overexpressed in C6 glioma cells, it appeared to have a tumour suppressive effect." (PMID 27229305, 2016). "Interestingly, these C6 glioma cells stably expressing Panx1-GFP were also used to demonstrate in a later report, that Panx1 expression can accelerate the assembly of multicellular tumor aggregates through an interaction with F-actin microfilaments." (PMID 27229305, 2016). "Rat C6 glioma cells appear to acquire the ability (albeit a weak one) to pass sulforhodamine 101 when Panx1 is introduced, and the human prostate adenocarcinoma line LNCaP shows increased movement of calcium between neighboring cells following Panx1 transfection." (PMID 24600404, 2014).
glioma (continued). "Moreover, this may confirm the hypothesis of the tumor-suppressive activity of Panx-1 reported in the C6 glioma cell line, adenocarcinoma of gallbladder and basal and squamous cell carcinoma of skin." (PMID 36833374, 2023). "However, as Panx1 has also been suggested to act as a tumor suppressor in gliomas, and squamous and basal cell carcinomas, the role of Panx1 may be dependent on the type of cancer or stage of disease." (PMID 27099931, 2016). "In fact, one of the first papers involving Panx1 and cancer reported that while Panx1 mRNA was expressed in primary astrocytes, it was not expressed in the C6 rat glioma cell line." (PMID 27229305, 2016). "Paradoxically, the authors reported four human glioma cell lines (U87, U251, SF188 and SF539) that were all positive for Panx1 at the transcript level, indicating that there might be some differences among species in terms of Panx1 expression in gliomas." (PMID 27229305, 2016). "However, the authors also found that rat C6 glioma cells lacked Panx1, and upon overexpressing green fluorescent protein (EGFP) -tagged Panx1 they observed a reduction in several cancerous properties of the rat cells, as well as increased gap junction communication." (PMID 30654593, 2019).
Sepsis (15 papers, 2019 to 2025). Sepsis is defined as life-threatening organ dysfunction caused by a dysregulated host response to infection. "Inhibiting Panx1 hemichannels emerges as a promising therapeutic strategy against sepsis and sepsis-associated MODS; however, further research is essential before its clinical translation can be realized." (PMID 37711629, 2023). "Inhibition of Panx1 conferred protection against sepsis-associated encephalopathy and mortality." (PMID 39763679, 2024). "Accumulating evidence has implicated the involvement of Panx1 in sepsis-associated MODS." (PMID 37711629, 2023). "The understanding of Panx1’s role in endothelial permeability and leakage is an area of ongoing research, and further investigations are needed to comprehensively unravel its involvement in the complex processes underlying sepsis-induced microcirculation disruption." (PMID 37711629, 2023). "Cx43 and Panx1 hemichannels play critical roles in regulating innate immunity during sepsis partly by mediating the release of ATP and other inflammatory signals." (PMID 39763679, 2024). "Various inhibitors of Cx43 and Panx1 have shown promise in modulating inflammation across sepsis and other disease models." (PMID 39763679, 2024). "This differential regulation of Panx1 expression suggests its tissue-dependent roles in sepsis and other inflammatory diseases." (PMID 39763679, 2024). "For example, Panx1 has been shown to exacerbate the inflammatory response in animal models of sepsis by promoting the excessive release of ATP, thereby enhancing innate immune cell recruitment and activation." (PMID 39763679, 2024). "Mimetic peptides targeting specific regions of Cx43 and Panx1 can distinctly modulate hemichannel activity in vitro, and diversely impact sepsis-induced lethality in vivo." (PMID 39763679, 2024). "Below we discuss the distinct and shared roles of Cx43 and Panx1 in modulating innate immunity during sepsis, emphasizing their tissue-specific contributions to inflammation and sepsis progression." (PMID 39763679, 2024). "In animal models of sepsis, Panx1 expression exhibits tissue-specific regulation, with upregulation observed in certain tissues like the heart and downregulation in others, such as the lung and spleen." (PMID 39763679, 2024). "Macrophage hemichannel molecules, such as Cx43 and Panx1, have emerged as pivotal regulators of ATP release, which amplifies innate immune responses in conditions such as sepsis, rheumatoid arthritis, and other inflammatory diseases." (PMID 39763679, 2024). "Given its significant involvement in various critical processes, Panx1 represents a promising therapeutic target for sepsis and MODS." (PMID 37711629, 2023). "More comprehensive research is needed to elucidate Panx1’s role and potential as a therapeutic target in sepsis and sepsis-induced MODS." (PMID 37711629, 2023). "This makes Panx1 an intriguing potential therapeutic target for sepsis and sepsis-induced MODS, offering a fresh approach to therapeutic interventions against these challenging disorders." (PMID 37711629, 2023). "This comprehensive review delves into the potential roles of Panx1 in the pathogenesis of sepsis, examining its contribution to the excessive inflammatory response in the early phase, immunosuppression in the late phase, and impairment of microcirculation." (PMID 37711629, 2023). "As the scientific investigation on Panx1 hemichannels in sepsis is limited, it becomes crucial to explore its distinct functions at different phases of sepsis and understand how it contributes to organ injuries." (PMID 37711629, 2023). "Panx1 primarily exacerbates injury and hinders recovery, making it a potential target for sepsis-induced MODS." (PMID 37711629, 2023). "The role of Panx1 in the heart during sepsis and its potential therapeutic efficacy remains to be discovered due to a lack of studies in this specific context." (PMID 37711629, 2023).
Sepsis (continued). "Given its role in promoting microthrombosis, Panx1 represents a critical factor in the delicate balance between beneficial coagulation and harmful microcirculation disruption during sepsis." (PMID 37711629, 2023). "Collectively, we reported low PANX1 expression in donor grafts prior to LT and decreased IL‐33 levels after LT in clinical patients with sepsis." (PMID 35593197, 2022). "We initially observed low expression levels of proteins involved in the PANX1–IL‐33 axis in clinical patients with sepsis after LT." (PMID 35593197, 2022). "There is only one study that demonstrated the expression of Panx1 in the human kidney, in which Panx1 was mentioned to be present mostly in tubular cells and its expression was increased in the renal tissue of patients with sepsis-related AKI." (PMID 35625681, 2022). "Collectively, we demonstrated the vital role of the PANX1–IL‐33 axis in sepsis and related liver injury using clinical samples." (PMID 35593197, 2022). "Probenecid, which is an inhibitor of the pannexin 1 hemichannel, has been demonstrated to attenuate cognitive impairment after cecal ligation and puncture (CLP)-induced sepsis in mice by inhibiting pannexin 1-dependent ATP release in the hippocampus." (PMID 34712121, 2021). "In LPS-induced sepsis mouse models, the ablation of pannexin-1 significantly reduced mice mortality, which indicates the role of pannexin-1 in non-canonical inflammasome activation." (PMID 33424864, 2020). "In a sharp contrast, CLP significantly increased Panx1 mRNA expression levels in the heart, suggesting a tissue-specific divergent regulation of Panx1 during lethal sepsis." (PMID 30655582, 2019). "To assess the role of Panx1 in lethal sepsis, we examined the impact of Panx1 mimetic peptide on the outcome of CLP-induced lethal sepsis." (PMID 30655582, 2019). "In animal model of experimental sepsis, Panx1 expression was significantly elevated in the heart, and a Panx1-specific mimetic peptide 10Panx reproducibly exacerbated the outcome of lethal sepsis." (PMID 30655582, 2019). "At relatively lower doses (10, 50, and 100 mg/kg), the Panx1 mimetic peptide, 10Panx, reproducibly exacerbated the sepsis-induced animal lethality, reducing survival rates from 60–70% to 0–10%." (PMID 30655582, 2019). "Here we demonstrated that during experimental sepsis, Panx1 mRNA expression was significantly elevated in the heart, but decreased in the kidney, lung, and spleen." (PMID 30655582, 2019). "In animal model of lethal sepsis, Panx1 expression levels were significantly elevated in the heart, but reduced in the kidney, lung, spleen, and blood." (PMID 30655582, 2019). "To understand the role of Panx1 in lethal sepsis, we examined the possible change in its expression levels using a clinically relevant animal model of lethal sepsis induced by a surgical procedure termed cecal ligation and puncture (CLP)." (PMID 30655582, 2019). "Collectively, these findings suggested that elevated macrophage Panx1 expression and hemichannel activation contribute to the pathogenesis of lethal sepsis." (PMID 30655582, 2019). "Panx1 can be activated by caspase-11, an inflammation-related enzyme that is typically not expressed under normal conditions but is induced by lipopolysaccharide (LPS) during sepsis." (PMID 41041630, 2025). "While Cx43 and Panx1 share roles in mediating ATP release and promoting inflammation, they display distinct regulatory mechanisms and tissue-specific expression patterns during sepsis." (PMID 39763679, 2024). "Divergent regulation of Cx43 and Panx1 expression in sepsis." (PMID 39763679, 2024). "Therefore, further evidence is required to understand the pattern of Panx1 hemichannel activation in sepsis before exploring its clinical therapeutic potential." (PMID 37711629, 2023). "Furthermore, Panx1’s involvement in developing systemic inflammatory disorders, such as sepsis, has been investigated." (PMID 37711629, 2023).